CTLA4 (cytotoxic T-lymphocyte associated protein 4)
Diseases named in the same sentence as CTLA4 in open-access papers (continued):
Sharing a sentence is not in itself a finding about the gene and the disease.
tumor (continued). "The link between autoimmunity and neoplasia is further supported by increased risk of lymphoma and gastric cancer in individuals with mutated CTLA-4 and, consequently, with dysregulated immune responses." (PMID 39359726, 2024). "We conducted an analysis and visualization of tumor immune escape and immunotherapy for (CTLA-4)-related lncRNAs in high-risk and low-risk subgroups." (PMID 39143529, 2024). "Similar frequencies of isolated or combined genotypes of the CTLA-4 variants were seen in patients stratified by tumor location, histological type, Clark level, and stage." (PMID 39596391, 2024). "Like PD-1 and CTLA-4, continuous tumor-associated antigens exposure can result in high and sustained expression of LAG-3 on CD4+ and CD8+ T cells, which negatively regulate T cell expansion and lead to immune disorders, mainly manifested as T-cell exhaustion." (PMID 39252941, 2024). "These chronic HS dietary conditions were also associated with enhanced expression of inhibitory CTLA4 on tumor-infiltrating T-lymphocytes." (PMID 38891044, 2024). "These ligands inhibit anti-tumor effector cells via programmed cell death protein 1 (PD-1) and cytotoxic T-lymphocyte-associated protein 4 (CTLA-4)." (PMID 38727262, 2024). "As an ICI, CTLA-4 decreases the immune response, and its increased expression can help the tumour to modify the immune response, hence causing a greater disease burden." (PMID 38978137, 2024). "Knockdown of the NR4A genes in intratumor Tregs attenuates Treg activity with the decrease of Foxp3 and CTLA-4 and develops effective T helper cell (Th) 1 and CTLs-associated anti-tumor immunity." (PMID 39227959, 2024). "For certain patients with low PD-L1 expression, CTLA-4 reduces the risk of resistance to PD-1 and demonstrates synergistic anti-tumor effects." (PMID 38762484, 2024). "Programmed cell death protein 1 (PD-1) and cytotoxic T-lymphocyte-associated protein-4 (CTLA-4) are immune checkpoints that abrogate anti-tumor immune response." (PMID 39682130, 2024). "A clinical trial of first-line durvalumab and tremelimumab with chemotherapy in RAS-mutated metastatic CRC underlined that CTLA4 expression at the tumor site was associated with better response." (PMID 39499374, 2024). "The reasons for these differences are diverse; for example, the origin of the tumor can affect the results of meta-analyses, so we conducted subgroup analyses of CTLA4 polymorphisms by cancer type." (PMID 39464701, 2024). "Additional studies have examined the expression of PD-L1 and CTLA-4 in tumor-associated macrophages (TAMs)." (PMID 38275869, 2024). "As an example, ablation of α-SMA CAFs in a genetic PDAC model (PKT: Ptf1acre/+; LSL-KrasG12D/+; Tgfbr2flox/flox) suppressed fibrosis and accelerated tumour growth, but it also was sensitised to anti-CTLA-4 therapy, associated with increased inflammation." (PMID 38791926, 2024). "The correlation of CD86 and CD80 with clinical outcome in canine histiocytic disease has not been reported so far, however the expression of their receptor CTLA-4 on tumor cells is associated with a worse prognosis in other malignant tumors in dogs." (PMID 38962703, 2024). "In summary, in the subcutaneous setting, combined RASG12C(ON) and SHP2 inhibition renders immune-excluded NSCLC tumours responsive to anti-PD-1 immunotherapy, with further addition of anti-CTLA-4 causing eradication of most tumours." (PMID 39322643, 2024). "Dendritic cells express programmed death ligand 1 and the ligand for cytotoxic T-lymphocyte-associated protein 4, inducing to down-regulation of antigen processing and inhibition of the effector function of tumor-infiltrating lymphocytes." (PMID 38611634, 2024).
tumor (continued). "Anti-CTLA-4 and anti-PD-1 therapies frequently cause rashes, pruritus, and vitiligo, which is linked to improved tumor responses in melanoma." (PMID 39682118, 2024). "This strain colonizes at tumor cells and releases nano-antibodies targeting programmed cell death-ligand 1 (PD-L1) and cytotoxic T lymphocyte-associated protein-4 (CTLA-4) using a stabilized lysing release mechanism." (PMID 38543481, 2024). "Tumor cells express immune checkpoints such as the ligand of programmed death protein 1 (PD-L1), cytotoxic T lymphocyte-associated antigen-4, (CTLA-4), and lymphocyte activation gene 3 (LAG3), which inhibit the immune response." (PMID 38339348, 2024). "Control, anti‐CD8, and APG‐157 + anti‐CTLA‐4 + anti‐CD8 groups had tumor cell growth demonstrating loss of anti‐tumor activity when CD8+ T cells were depleted for the APG‐157 + anti‐CTLA‐4 treatment group." (PMID 38686626, 2024). "Subsequently, there was a significant lull in the development of tumor immunotherapy until the breakthrough discoveries of anti-CTLA4 (cytotoxic T-lymphocyte-associated protein 4) in 1987 and anti-PD1 (programmed cell death protein 1) in 1992." (PMID 39456702, 2024). "Among the numerous tumor-associated immune checkpoints, CTLA-4 and PD-1 are two critical molecules, and targeting them has demonstrated effectiveness in promoting the activation of anti-tumor immune responses." (PMID 38415258, 2024). "The activated antitumor immunity, elevated PD-L1, PD-L2 and CTLA-4 expression, and heightened tumor immunogenicity likely explain why the low-risk group benefits from ICI therapy compared to their high-risk counterparts." (PMID 38994371, 2024). "HIF1-α upregulates immunomodulatory surface ligands such as cytotoxic T-lymphocyte-associated protein 4 (CTLA-4) and programmed death-ligand 1 (PD-L1), inhibiting efficient anti-tumor immune responses." (PMID 38610954, 2024). "Low muscle was also associated with higher CTLA4 expression in tumor (log2-fold change = 0.53, p = 0.0589)." (PMID 39769193, 2024). "Other strategies adopted by tumor cells are the upregulation of the so-called immune checkpoint molecules, such as cytotoxic T-lymphocyte-associated protein 4 (CTLA-4) and programmed cell death protein 1 (PD-1) with its ligand (PD-L1)." (PMID 38672372, 2024). "Tumor-infiltrating immune cell levels, the expressions of immune checkpoints including PD-1, PD-L1 and CTLA-4, and TMB were found to be elevated in the high-risk group relative to the low-risk group, as classified by the genomic model-derived from DUSP5." (PMID 38872157, 2024). "TGF-β1 induces the expression of immune checkpoints such as programmed cell death protein 1 (PD-1) and cytotoxic T-lymphocyte associated protein 4 (CTLA4) on T cells, thereby attenuating T cell-mediated anti-tumor immune surveillance." (PMID 39001472, 2024). "Avelumab, durvalumab and atezolizumab inhibit binding of T cells to PDL-1 on the tumor surface and ipilimumab, among others, targets cytotoxic T lymphocyte-associated antigen-4 (CTLA-4)." (PMID 37955712, 2024). "Tumor associated macrophages can also upregulate the expression of inhibitory receptors PD-1 and CTLA-4 in T cells." (PMID 38762825, 2024). "In recent years, the development of immune checkpoint inhibitors (ICIs), such as anti-cytotoxic T lymphocyte-associated protein 4 and anti-PD-1/PD-L1, has led to significant breakthroughs in anti-tumor therapy." (PMID 39263534, 2024). "SQLE was also significantly associated with tumor-immune cell infiltration, immune checkpoints including PD-1 and CTLA-4, and biomarkers of the tumor-immune microenvironment." (PMID 38612682, 2024). "These therapies primarily target immune checkpoint proteins located on the surface of tumor cells, such as Programmed Death-1 (PD-1) and Cytotoxic T lymphocyte-associated protein 4 (CTLA-4)." (PMID 39234260, 2024).
tumor (continued). "Intriguingly, the cytotoxic T-lymphocyte-associated antigen 4 (CTLA4) antibody (Ab) has been identified to stimulate Fc receptor-mediated active phagocytes in the tumor microenvironment, thereby generating “eat me” signals." (PMID 38398223, 2024). "Various ICIs have been discovered to inhibit specific proteins (e.g., cytotoxic T-lymphocyte-associated antigen 4 (CTLA-4) and programmed cell death protein 1 (PD-1) in tumor-immune environments and thereby eliminate tumor cells." (PMID 39408929, 2024). "The ligands of tumor cells bind to checkpoint proteins such as cytotoxic T-lymphocyte-associated protein 4 (CTLA-4), programmed cell death protein 1 (PD-1), and lymphocyte activation gene-3 (LAG-3)." (PMID 39441327, 2024). "Using cancer genomic datasets from cBioPortal, we identified a series of point mutations in the cytoplasmic domain of CTLA-4, detected in tumor samples." (PMID 38542966, 2024). "ICIs enhance antitumor immunity by blocking immune checkpoint molecules expressed on the surface of T lymphocytes and tumor cells, such as cytotoxic T lymphocyte-associated antigen 4 (CTLA-4), programmed cell death protein 1 (PD-1), and its ligand (PD-L1)." (PMID 39518012, 2024). "Nonetheless, either intratumoral or systemic treatment of STING agonist was associated with increased expression of CTLA-4 on tumor-infiltrating T cells." (PMID 39113096, 2024). "This approach can significantly boost their anti-tumor immune response, potentially surpassing the efficacy of PD-1 and cytotoxic T lymphocyte-associated antigen-4 (CTLA-4) monoclonal antibody therapies." (PMID 39030523, 2024). "It is probable that our findings of a lack of tumor-infiltrating lymphocytes and the weak IFN-γ signature of MucM are associated with this tumor’s relative resistance to anti–PD-1 and anti–PD-1+anti–CTLA-4 as compared with CM tumors." (PMID 39513365, 2024). "Therapies that target immune checkpoints, such as programmed cell death-1 (PD-1) and CTL-associated antigen-4 (CTLA-4), have been approved for use in a variety of tumor types, including NSCLC." (PMID 38927911, 2024). "ICI therapy for CCA patients carries promise, given some of the tumours' immunologic features, including the expression of immune checkpoint molecules, such as PD‐L1 and cytokine T‐lymphocyte‐associated protein 4 (CTLA‐4) within the tumour microenvironment." (PMID 39223878, 2024). "The ensuing deprivation of costimulatory signals to T cells was eventually linked to the finding that anti-CTLA-4 antibodies result in tumor regression in preclinical mouse models." (PMID 38732242, 2024). "Tumor-infiltrating Tregs express high levels of cell surface molecules associated with T-cell activation, such as CTLA4, PD-1, LAG3, TIGIT, ICOS, and TNF receptor superfamily members including 4-1BB, OX40, and GITR." (PMID 37182149, 2023). "We examined the expression levels of PD-1 (PDCD1), PD-L1, and CTLA4 (cytotoxic T-lymphocyte associated protein 4) in tumor and normal groups." (PMID 37251440, 2023). "We showed that the adjuvant activity of Ad-α-CTLA-4 is independent from the vaccine antigen as it improved the immune response and efficacy of an Adenovirus based polyepitope vaccine encoding tumor neoantigens." (PMID 37180141, 2023). "ONCR-177 also encodes five transgenes intended to boost anti-tumor immunity, including IL-12, Fms-like tyrosine kinase 3 ligand, C-C motif chemokine ligand 4, and antagonists to CTLA-4 and PD-1." (PMID 37841530, 2023). "Currently, there is no reliable biomarker predicting or correlating with irAEs, but several ones are under investigation including serum IL-6, IL-17, soluble CTLA-4 (sCTLA-4), absolute lymphocyte count, and tumor mutation burden." (PMID 37342323, 2023). "Radiation induced DNA damage activates DNA damage repair pathways that causes upregulation of CTLA-4 and PD-L1 expression causing immunosuppression within the tumor microenvironment and blunting the effects of ICI." (PMID 37554167, 2023).
tumor (continued). "With anti-PD1 and anti-CTLA4 treatments, a greater tumor TIDE prediction score is linked to a poorer ICB response as well as a worse patient survival." (PMID 36776843, 2023). "Although drugs targeting Tregs have not yet been approved, preclinical studies indicated that one of the mechanisms underlying the anti-tumor effects of anti-CTLA-4 mAb is Treg depletion." (PMID 37729184, 2023). "Cytotoxic T lymphocyte-associated antigen 4 (CTLA-4) can inhibit T lymphocyte activation and subsequently cause immune evasion in the tumor microenvironment." (PMID 37818195, 2023). "According to the DAMP-related signature, low-risk patients are candidates for ICI therapy because a higher TIDE score was associated with a greater likelihood of tumor immune escape and decreased benefit from anti-PD-1/CTLA4 therapy." (PMID 37259066, 2023). "Strong positive CTLA-4 expression was as well observed in epithelial cells of tumor-associated epithelium, showing a gradient of CTLA-4-staining from basal to upper epidermis in accordance to the maturation process." (PMID 37415208, 2023). "The discovery of immune checkpoint molecules such as programmed cell death protein 1 (PD-1) and cytotoxic T-lymphocyte-associated protein 4 (CTLA4) towards the end of the 20th century has led to an enhanced understanding of tumor immunosuppression." (PMID 37958421, 2023). "ICIs work by activating the anti-tumor activity of T-lymphocytes through the inhibition of the interaction between PD-1, PD-L1, and cytotoxic T lymphocyte-associated antigen-4 (CTLA-4)." (PMID 37612622, 2023). "Because immune checkpoint genes such as CD274 (PDL1) and CTLA4 can cause T-cell dysfunction, preventing cytotoxic T cells from targeting tumor cells and promoting tumor progression." (PMID 38071230, 2023). "A well-studied immune checkpoint is cytotoxic T lymphocyte-associated antigen-4 (CTLA-4), which primarily regulates T-cell activity in the early tumor microenvironment and has a strong correlation with T cells in all cancer types." (PMID 37371458, 2023). "In fact, increased expression of CTLA-4 is associated with diminished immune defense against the tumor." (PMID 38406785, 2023). "The cytotoxic T lymphocyte-associated antigen 4 (CTLA-4) is an additional negative regulator of immune effectors exploited by tumor cells." (PMID 38115743, 2023). "For instance, cytotoxic T lymphocyte-associated antigen-4 (CTLA-4) was found to downregulate immune responses and is closely related to tumor progression." (PMID 37454878, 2023). "Novel ICP receptors, which include programmed death 1 (PD-1) and its ligand (PD-L1), and cytotoxic T-lymphocyte-associated antigen 4 (CTLA-4), are shown to suppress T cells presented at the tumor site." (PMID 37735656, 2023). "In tumor cells, RIG-I activation has been shown to induce immunogenic cell death, which promotes cross-presentation of tumor-associated antigens through bystander DCs and augments the efficacy of CTLA-4 checkpoint blockade." (PMID 36319717, 2023). "The discovery of ICI, such as anti‐PD‐1, anti‐PD‐L1, and anti‐CTLA4, allowed the development of treatments that can significantly generate antitumor activity, especially in tumors with high tumor mutational burden (TMB)." (PMID 38037752, 2023). "Unfortunately, except for mismatch repair deficiencies, PDAC tumours largely resist CTLA-4 inhibitor monotherapy." (PMID 37686543, 2023). "For example, CTLA-4, a cytotoxic T-lymphocyte-associated antigen expressed on T cells, inhibits its activation following interaction with tumor-resident immunosuppressive myeloid populations." (PMID 37376141, 2023). "A low CDS score indicated a higher PD1 and CTLA4 immunophenoscore, higher tumor mutation burden score, lower tumor immune dysfunction and exclusion score, and lower tumor escape score in OC, demonstrating a better immunotherapy response." (PMID 37868825, 2023).
tumor (continued). "Beyond PD-1/PD-L1, the expression of cytotoxic T-lymphocyte-associated Protein 4 (CTLA-4) in RCC tumor-infiltrating monocytes was identified as an independent prognostic factor in RCC patients and significantly associated with worse outcome." (PMID 37350955, 2023). "We observed an association between the expression of CTLA-4 in the T cell and antigen-presenting cell of the tumor microenvironment with Ann Arbor stage and IPS score at presentation." (PMID 37305822, 2023). "ICI works by targeting the programmed cell death 1 receptor (PD‐1), programmed cell death ligand 1 (PD‐L1), and cytotoxic T lymphocyte‐associated protein 4 (CTLA‐4), activating effective T cells, and killing tumor cells." (PMID 37724594, 2023). "One promising approach is to use a gene editing approach to eliminate the expression of immune checkpoint proteins (PD-1, CTLA-4, etc.), thereby making them less susceptible to the tumor microenvironment." (PMID 37345050, 2023). "Primes anti-tumor immune response by inhibiting the cytotoxic T-lymphocyte-associated protein 4 (CTLA-4) signaling pathway." (PMID 36675114, 2023). "In this regard, anti-programmed cell death 1 (PD-1)/PD-L1 and anti-cytotoxic T lymphocyte-associated protein 4 (CTLA-4) therapies have been demonstrated to elicit dramatic tumor regression in some patients." (PMID 36672244, 2023). "Recently, the role of immunotherapy in tumor treatment has been widely investigated, especially for cytotoxic T-lymphocyte associated protein 4 (CTLA-4) and programmed cell death-1 (PD-1) inhibitors." (PMID 37842200, 2023). "IFN-γ expression in tumor cells was found in 37 GCs and was positively associated with CTLA4+ lymphocytes in the LN (p = 0.027) and CTLA4+/IFN-γ+ in tumors and the LN (all p < 0.001)." (PMID 36979688, 2023). "Immune checkpoint surface receptors, such as programmed cell death protein 1 (PD-1) and cytotoxic T-lymphocyte-associated protein 4 (CTLA-4), are expressed by tumor cells to avoid antitumor activity by T cells." (PMID 36975459, 2023). "Some are designed to block the immune evasion of tumor cells, and these therapies are represented by ICIs, most of which target PD-1, PD-L1, cytotoxic T lymphocyte-associated protein 4 (CTLA-4), and other related checkpoints." (PMID 37612741, 2023). "The anti-PD-1/anti-CTLA4 immunotherapy, tumor mutational burden, medication sensitivity, and cancer stem cell index were compared between the high- and low-risk score groups." (PMID 37717019, 2023). "Co-expression of PD-1 with CTLA-4 on tumour-infiltrating lymphocytes (TILs) has also been linked to a better survival of patients." (PMID 37760457, 2023). "Our study found that low-risk patients had a lower tumor purity and benefited more from PD-1 and CTLA-4 antibodies, providing a theoretical foundation for the clinical application of ICI." (PMID 37955668, 2023). "The analysis deduced that tumor samples from patients in the low-risk group were more likely to exhibit favorable immune responses to PD-1/PD-L1 or CTLA4 inhibitors, or a combination thereof." (PMID 37796202, 2023). "More specifically, CT26 cells show statistically significant reductions in tumor volumes in response to murine anti-cytotoxic T-lymphocyte-associated protein-4 (CTLA-4) treatment and anti-PD-1 treatment." (PMID 37887283, 2023). "Its engagement with CD28 and PD-L1 is associated with T cell activation, while it’s binding with CTLA-4 can lead to co-inhibition of T cells leading to tumor immune escape and progression." (PMID 37256148, 2023). "Overexpression of PD-1 and CTLA-4 is recognized as a vital suppressor of anti-tumor immunity and is associated with better therapy response." (PMID 36998469, 2023). "The suggested immunotherapeutic strategies, which are known as immune checkpoint inhibitors (ICIs), target and block the inhibitory T-cell receptor PD-1 or cytotoxic T-lymphocyte-associated antigen 4 (CTLA-4) to restore tumor-specific T-cell immunity." (PMID 36765892, 2023).